TNF (tumor necrosis factor)
Diseases named in the same sentence as TNF in open-access papers (continued):
Sharing a sentence is not in itself a finding about the gene and the disease.
glioma (continued). "In contrast cytokines IFN-α, TNF-α,IL-12p70, IL-1β, IL-6, IL-8 and IL-10, as well as metalloproteinases -2 and -9 were present in equalamounts in glioma C6 and astrocyte CMs." (PMID 23637756, 2013). "Their results showed heat-regulated expression of TNF-alpha protein in the tumor and subsequent retardation of glioma growth." (PMID 24202446, 2013). "The combination effect was evaluated by the level of GFP and TNF expression in a human glioma cell line, and the mechanism of MMC effects on rAAV mediated gene expression was investigated by AAV transduction related signal molecules." (PMID 24451124, 2013). "It has been shown that glioma patients have elevated levels of inflammation serum markers such as IL-6, TNF-α, and reactive protein C." (PMID 23533307, 2013). "Glioma cell lines treated with TNF-α (10 nM, used as positive control in wound-healing assays) showed decrease in size of the wound as early as 12 h." (PMID 23855374, 2013). "Cultured human (U87-MG and U251-MG) and murine glioma cells (GL261) were treated with TNF-α for various times, and phosphorylation of NF-κB p65 protein was examined." (PMID 24244348, 2013). "In GL261 glioma cells, TNF-α-induced NF-κB activation was observed at 1 h, and STAT3 activation at 6 h." (PMID 24244348, 2013). "TNF-α peaks at the end of the first phase, then gradually decreases presumably due to the consumption by glioma cells (e.g., rebind to TNF receptors and trigger the secondary signaling cascades)." (PMID 22319429, 2012). "TNF-α knockout mice implanted with GL261 glioma cells have been shown to harbor a decreased number of tumor-associated macrophages and exhibit shorter survival." (PMID 22190972, 2011). "It therefore seems unlikely that NADPH oxidase functions at a point of these kinases in TNF-α-induced IL-6 synthesis in C6 glioma cells." (PMID 20205746, 2010). "The action point of NADPH oxidase in TNF-α-stimulated IL-6 synthesis in C6 glioma cells was investigated." (PMID 20205746, 2010). "In gliomas, TNF-α is shown to reduce growth and prolong survival by enhancing macrophage recruitment and microcyst formation." (PMID 17565690, 2007). "This study demarcates the functional roles for CDKIs-p21cip/waf1 and p27kip1 during TNF-α stimulated responses in LN-18 glioma cells." (PMID 17565690, 2007). "In conclusion, this study demarcates the functions of CDKIs-p21cip/waf1 and p27kip1 during TNF-α stimulated responses in LN-18 glioma cells." (PMID 17565690, 2007). "Also consistent with bulk-sorted TAM-MGs from low-grade gliomas, TNF alpha signaling via NFKB was the most XY-biased gene set in TAM-MGs in the scRNA-seq." (PMID 38895459, 2025). "TNF-α inhibition prolonged survival in a mouse glioma model." (PMID 42135822, 2025). "Interestingly, expression of the pro-inflammatory genes IL6 and TNF increased in grade II-III gliomas compared to control microglia, but decreased in GBM, highlighting the dynamic nature of TAM-MG gene expression during tumor progression." (PMID 38895459, 2025). "Our data highlight the TNF-α, IL-1β axis as a critical mediator of glioma progression." (PMID 40565357, 2025). "Gene set enrichment analysis (GSEA) showed that low levels of ROR-α expressions were linked with the TNF-induced signalling cascade, and glioma samples showed a negative relationship between TNF-α as well as ROR-α." (PMID 40495887, 2025). "A crucial role of inflammatory mediators in glioma biology has been described for TNFα." (PMID 39921723, 2025). "Future studies employing single-cell RNA-seq or spatial transcriptomics could clarify the cellular origins of TNF-α, IL-1β in gliomas and their interaction with infiltrating immune cells." (PMID 40565357, 2025). "Notably, there was overexpression of various cytokines, including IL-1β, IL-4, IL-6, IL-8, IL-10, TGF-β and TNF in the patient cohort, which was unsurprising given that these cytokines serve primarily immunosuppressive roles in the glioma microenvironment." (PMID 41034696, 2025).
glioma (continued). "Collectively, these observations support the hypothesis that DNA methylation status plays a significant regulatory role in the expression of TNF-α signaling components during glioma progression." (PMID 40565357, 2025). "TNF-α is a pleiotropic cytokine that, while capable of inducing apoptosis under certain conditions, predominantly fosters tumor survival and immune evasion in the glioma context through NF-kB, MAPK, and JNK signaling." (PMID 40565357, 2025). "In vitro, HTLV-1-infected glioma stem cells (GSCs) alter glutamate metabolism and increase production of granulocyte-macrophage colony-stimulating factor (GM-CSF), Tumor Necrosis Factor-alpha (TNF-α), IL-1α, and IL-6." (PMID 40563634, 2025). "Attenuated CSMD1 expression in HGG samples may modify the cytokine profile of glioma cells induced by TNF, thereby potentially aligning with the immunosuppressive phenotype in the glioma microenvironment." (PMID 38561856, 2024). "The induction of necroptosis via exogenous signals such as tumor necrosis factor (TNF) or chemotherapeutic agents can lead to irreversible cell death in glioma cells, coupled with a potent inflammatory response that augments the immune system’s ability to target tumor cells." (PMID 39184045, 2024). "Furthermore, overexpression of CSMD1 in glioma cell lines suppressed the aggressive phenotype and TNF/P65/IL-6 and IL-8/STAT3 pathways." (PMID 38561856, 2024). "Therefore, we treated glioma cells with temozolomide and/or lomustine in combination with TNF and compared the response of Ctrl and CSMD1-overexpressing clones." (PMID 38561856, 2024). "Western blot and ELISAs showed that TNF-α was present inside glioma-derived exosomes." (PMID 39088270, 2024). "This mitigates the invasive properties of glioma cells often exacerbated by TNF signaling." (PMID 39769099, 2024). "In addition, EGFR + TNF inhibition is more effective than temozolomide treatment in glioma cells where methylguanine methyltransferase (MGMT) is unmethylated, whereas it is comparable in MGMT methylated cells." (PMID 38561856, 2024). "Gene set enrichment analysis (GSEA) revealed alterations in the genes overlapping with CNS tissue and CNS cancer cell lines, as well as the signaling pathways, such as interferon signaling, TNF signaling, and the metabolic pathways, which are deregulated in multiple malignancies." (PMID 39796709, 2024). "In addition, interleukin(IL)-1β and TNFα expression levels were evaluated on glioma cells after KPF-BBR and KPF-ABR treatments." (PMID 37445894, 2023). "Glioma-derived factors, such as IL-1β, IL-6, IL-8, and TNFα, are crucial inflammatory mediators that trigger the inflammatory cycle in GBM and also promote carcinogenesis by avoiding growth suppression and apoptosis, inducing angiogenesis and metastasis and maintaining cancer cell stemness." (PMID 38003396, 2023). "Glioma-related studies have shown that lysosomal peptidases are not regulated upstream of TNF-α, and, in gliomas, TNF-α activates cathepsin B/D to mediate cell necrosis, causing RIP1 and RIP3 kinases–driven necroptosis." (PMID 37398678, 2023). "Most glioma cells are insensitive to the proapoptotic effects of TNF-α." (PMID 36675073, 2023). "However, the intricate relationship between GPCR, TNF, and coagulation in glioma requires further investigation in future studies." (PMID 37560473, 2023). "In glioma immunotherapy, TNF is predominantly utilized in gene therapy." (PMID 38259287, 2023). "Additionally, a study by Sarkar and Yong showed that increases in IL-1β and TNF-α levels were positively correlated with glioma cell invasiveness and a corresponding elevation of MMP-2 and MMP-9 proteins." (PMID 36675073, 2023).
glioma (continued). "Apart from tumor suppressor genes and signaling proteins, many cytokines, for example tumor necrosis factor alpha (TNFα), interferons- beta/gamma (IFNβ/γ), and interleukins (IL-12) helped increasing the survival rates by suppressing the tumorigenicity in glioma disease models and human patients." (PMID 37335084, 2023). "The decrease in TNFα signaling via NF-κB and the increase in peroxisome in the best-performing patients could indicate a possible relationship to glioma stem cell burden, tumor invasion, and RT response resulting in a more favorable outcome." (PMID 37637066, 2023). "Specifically, we discovered CLDN4/TNF-α/NF-κB signal axis in glioma for the first time." (PMID 35418179, 2022). "Our research showed that ANXA1 is translocated to the nucleus in glioma cells exposed to TNF-α." (PMID 35415239, 2022). "Our initial finding was that hypoxic glioma‐derived EVs could promote macrophages M2 polarization, as evidence by decreased expression of iNOS and TNF‐α as well as elevated expression of Arg‐1 and IL‐10." (PMID 36052751, 2022). "Thus, before initiating treatment, high levels of IL-6, IL-8, IL-17, IL-33, TNF-α, TGF-β, and CRP in the circulation are strongly associated with increased glioma stem cell activity that potentially leads to glioma progression and greater invasiveness." (PMID 35054779, 2022). "As the P65 and Akt signalling pathways contribute to the proliferation of glioma cells stimulated with TNF-α, we sought to determine whether these signalling pathways are regulated by ANXA1." (PMID 35415239, 2022). "For the downregulated genes in Ad-SGE-REIC-treated U87ΔEGFR glioma brain tissue compared with the control, 24 significantly enriched pathways were identified, including the TNF-alpha NF-kB Signaling Pathway, Mitochondrial Gene Expression, and Wnt Signaling Pathway NetPath." (PMID 36006934, 2022). "CCK-8 analysis demonstrated that TNF-α stimulation promotes rapid growth in glioma cells." (PMID 35415239, 2022). "Some evidence indicates that TNF-α is a double-edged sword that may exert dual effects on drug resistance, recurrence, and metastasis of glioma." (PMID 35415239, 2022). "Based on this property, we explored whether ANXA1 translocates to the nucleus in glioma cells treated with TNF-α." (PMID 35415239, 2022). "Let-7 miRNA, specifically ones carrying the core sequence motif UUGU, can activate microglial and BMDM Toll-like receptor (TLR) 7 and induce TNF-α production which might lead to suppression of glioma growth." (PMID 36555253, 2022). "SLC39A7 promotes malignant behaviors in glioma via the TNF-α-mediated NF-κB signaling pathway." (PMID 35945192, 2022). "TAMs could produce pro-inflammatory mediators including TNF-α, IL-6, and IL-12 to amplify inflammation in gliomas." (PMID 36468012, 2022). "Since our previous study showed that TNF-α could promote proliferation and tumorigenesis via the NF-κB signaling pathway in glioma, we then detected downstream molecules' expression." (PMID 34149917, 2021). "In summary, we found that the zinc transporter SLC39A7 is highly expressed in high-grade glioma patients with a poor prognosis and can activate the TNF-α-mediated NF-κB signaling pathway, thereby promoting the proliferation, invasion and migration of glioma cells." (PMID 34149917, 2021).
glioma (continued). "Additionally, we show that TNFα expression is higher in the media from two primary glioma stem cell lines Mφ-GSC28 and Mφ-GSC267 compared to neural stem cell (NSC) control (Mφ-NSC)." (PMID 33853689, 2021). "In this study, the combination of Au–OMV and radiotherapy had a specific cytotoxic effect on GL261 glioma cells which may have been related to intracellular ROS production, chemotaxis of macrophages, and TNF-α production." (PMID 34202555, 2021). "Furthermore, we detected the mRNA expression levels of SLC39A7 and TNF-α in 70 clinical glioma specimens." (PMID 34149917, 2021). "Likewise, TNFα also induces IL-6 production in a variety of cells, such as glioma cells, osteoblasts, and vascular smooth muscle cells, through distinct transduction pathways." (PMID 34831450, 2021). "In addition, tumor necrosis factor alpha (TNF-a) has been shown to promote glioma progression via the TNIP1-mediated TNF-a/NF-kB signaling pathway." (PMID 34899179, 2021). "Other liposomal formulations with modified surface and core include magnetite-core cationic liposomes that can be used to activate a heat-shock sensitive promoter in the DNA carried by the liposome, thus regulating expression of the therapeutic gene such as TNFα in glioma cells." (PMID 33790740, 2021). "In vitro experiments revealed that two major HRLs, LINC00941 and BASP1-AS1, could significantly affect the proliferation of glioma cells, in which EMT and TNF-α signaling pathway might be the underlying mechanism." (PMID 34659218, 2021). "However, TNF is also released by gliomas and plays an essential role in promoting tumorigenesis, proliferation, metastasis, and inhibiting apoptosis through the NF-κB signaling pathway." (PMID 34873410, 2021). "The results of sphere formation assays showed that 31.7 ± 7.6% (mean ± SD, n = 3) of glioma cells still could form >40 um spheres after TNF-α/IL-6/sIL-6R treatment." (PMID 33227992, 2020). "This suggests that TNIP1 is a key regulator in the TNF‐α signalling pathway in glioma tissue." (PMID 31691497, 2020). "Combined, these results demonstrate that RGD4C-AAVP-TNF treatment of orthotopic glioma-bearing mice markedly suppressed tumor growth in a dose-dependent manner after sufficient TNF production to disrupt the tumor vasculature and to induce apoptosis in tumor cells." (PMID 31130731, 2020). "To ascertain whether emodin exerted an antitumor effect on glioma through the TNF-α/RIP1/RIP3 pathway in vivo, we established a xenograft model by subcutaneously injecting U251 cells into BALB/C-nu/nu nude mice." (PMID 30924024, 2020). "Thus, our investigation demonstrated that TNIP1 is an essential component for TNF‐α–induced phosphorylation and degradation of IκB‐α regulates glioma cell fate." (PMID 31691497, 2020). "Moreover, CCL2 expression in vitro was stimulated by pro-inflammatory cytokines IL-1β and TNFα in all glioma cell lines tested." (PMID 32456359, 2020). "Here, we revealed high levels of TNIP1 and TNF‐α/NF‐κB in glioma tissue." (PMID 31691497, 2020). "Furthermore, BACE2 knockdown suppressed the phosphorylation of IKKβ induced by TNF‐α in glioma cells." (PMID 31856384, 2020). "IL-6, TNF-α, and IL-12 are markers of M1-type macrophages that can repress glioma progression." (PMID 33363140, 2020). "However, when human monocytes were exposed to IL1β/IFN-γ, cytokines that are elevated in glioma subjects, or to the toll-like receptor-4 ligand LPS, demeclocycline elicited a further increase in TNF-α levels in activated cells." (PMID 32153581, 2020). "The results revealed that TNF-α/IL-6/sIL-6R could efficiently upregulate the expression of Il-6 more than IL-6/sIL-6R or IL-6 alone in glioma cells." (PMID 33227992, 2020). "IFNγ and TNF-α were produced when TGFβ-trapped CAR-Ts recognized target glioma cells." (PMID 32974124, 2020).
glioma (continued). "Furthermore, TGFβ1 stimulates BACE2 expression through Smad‐dependent signalling, which modulates TNF‐α‐induced NF‐κB activity through the PP1A/IKK pathway to promote tumorigenesis in glioma cells." (PMID 31856384, 2020). "Although TNIP1 and the TNF‐α/NF‐κB axis play key roles in immune diseases and inflammatory responses, their relationship and role in glioma remain unknown." (PMID 31691497, 2020). "The results demonstrate that emodin could induce necroptosis in glioma possibly through the activation of the TNF-α/RIP1/RIP3 axis." (PMID 30924024, 2020). "RT-PCR results showed that the level of Il-6 mRNA in U373-MG glioma cells was elevated approximately 1-, 2-, and 10-fold by IL-6, a combination of IL-6 and soluble IL-6 receptor (IL-6/sIL-6R), and TNF-α plus IL-6 and soluble IL-6 receptor (TNF-α/IL-6/sIL-6R), respectively." (PMID 33227992, 2020). "Furthermore, loss of TNIP1 disbanded the A20 complex responsible for IκB degradation and NF‐κB nucleus translocation, and consequently erased TNFα‐induced glioma cell proliferation." (PMID 31691497, 2020). "The TNF-α/IL-6/sIL-6R complex could more efficiently induce the expression of Il-6 than IL-6/sIL-6R or IL-6 alone in a tumorigenic C6 glioma cell line." (PMID 33227992, 2020). "Therefore, we demonstrated that TNF-α/IL-6/sIL-6R can differentiate C6 glioma cells more efficiently than IL-6/sIL-6R and IL-6 alone." (PMID 33227992, 2020). "Additionally, the total cell population and the tumorigenicity of glioma cells were all considerably reduced after TNF-α/IL-6/sIL-6R treatment." (PMID 33227992, 2020). "IL13Ra2-CAR.CD28.ζ T cell proliferation resulted in the production of IFN-γ and TNF-α as well as facilitated phenotypically proinflammatory glioma microenvironment by triggering elevated levels CD4+ and CD8+ T cells and CD8α+ DCs as well as a reduction in Ly6G+ MDSC levels." (PMID 33204365, 2020). "Thus, our investigation uncovered a vital function of the TNIP1‐mediated TNF‐α/NF‐κB axis in glioma cell proliferation and provides novel insight into glioma pathology and diagnosis." (PMID 31691497, 2020). "Moreover, TNF-α/IL-6/sIL-6R also decreased the total cell population and the tumorigenicity of glioma cells." (PMID 33227992, 2020). "Moreover, our results indicated that increased circulating IL‐6, IL‐8, IL‐17, TNF‐α, TGF‐β, and CRP levels are significantly associated with increased glioma risk." (PMID 31599129, 2019). "Moreover, we have extracted the patient prognosis survival data from TCGA survival database and confirmed that high expression of TNF-α improves glioma patient’s survival." (PMID 31216715, 2019). "In experiments using primary human T cells, CART-EGFRvIIIΔPD-1 cells were found to produce significantly greater amounts of Th1 proinflammatory cytokines (e.g., IFN-γ and TNF-α) when cultured with EGFRvIII-expressing glioma compared to CAR T cells expressing endogenous PD-1." (PMID 31727131, 2019). "All of these suggest that MALAT1 dependent EV-mediated microglia stimulation and IL-6, IL-8, and TNF-α secretion could contribute to glioma progression." (PMID 32117213, 2019). "TNF-α and IL-1β can serve as key prognostic biomarker in high-grade glioma and meningioma patients." (PMID 31653130, 2019). "Elevated TNF-α concentrations were observed in meningioma and glioma patients." (PMID 31653130, 2019). "In addition, we suggest here that NFATc3 is a key positive regulator of RCAN1-4, COX-2; TNF-α; CXCR-3, GM-CSF and IL-2, known to be implicated in glioma growth." (PMID 31249342, 2019). "Moreover, we found that increased circulating IL‐8, IL‐17, TNF‐α, and TGF‐β levels are significantly associated with glioma risk, which indicates that these inflammatory factors are involved in the pathogenesis of glioma." (PMID 31599129, 2019). "In glioma cells, Integrinα6β1 prevents TNF induced apoptosis." (PMID 31382980, 2019). "However, another study in murine glioma model found a decreased TNFα secretion in GAMs, interpreted as functional impairment." (PMID 30506802, 2019).